RELA (RELA proto-oncogene, NF-kB subunit)
Diseases named in the same sentence as RELA in open-access papers (continued):
Sharing a sentence is not in itself a finding about the gene and the disease.
prostate carcinoma (33 papers, 2005 to 2025). A carcinoma that arises from epithelial cells of the prostate gland. "In colon, breast, and prostate cancer cells, the RELA/p65 phosphomimetic mutation at Ser536 triggered dramatic apoptosis and suppressed tumor growth by affecting the expression of genes related to cell death or survival in nude mice." (PMID 35787690, 2022). "Of the different NF-κB family subunits, especially p52 has been shown to be important, but the transactivating subunits RelA, RelB and c-Rel have all also been implicated in prostate cancer." (PMID 30158439, 2018). "The prognostic value of RelA is in concordance with studies on prostate cancer, in which both nuclear and cytoplasmic RelA overexpression were linked to disease progression." (PMID 17622249, 2007). "Also, high nuclear RelA, together with high nuclear AR expression, is associated with poor prostate cancer outcome, indicating the existence of other relevant NF-κB/AR interactions." (PMID 30158439, 2018). "Phosphorylation of RelA/p65 Ser536 promotes apoptosis in cervical, colon, breast, and prostate cancers." (PMID 39498383, 2024). "Twenty percent of NF-κB transcription factor is inhibited using cationic cyclodextrin and anti-RelA siRNA in prostate cancer cells." (PMID 35631507, 2022). "High nuclear levels of RelB and RelA have been detected in human prostate cancer and are related to a poor prognosis in patients." (PMID 30361641, 2018). "While RelA has become a candidate prognostic marker of prostate cancer progression, little is known about the expression and the subcellular localisation of other NF-κB subunits." (PMID 16205698, 2005). "More recently, constitutive activation of NF-κB (RelA/p50) has been detected in androgen-independent prostate cancer cell lines as well as in prostate cancer tissues and appears to promote cell growth, survival, and metastasis." (PMID 16205698, 2005). "Protein encoded by RELA is a subunit of NFKB, which may have a potential role as prognostic biomarker in prostate cancer." (PMID 33066530, 2020). "The promotion of VSV oncolysis by vorinostat in prostate cancer cells was traced back to the reversible induction of NF-κB signaling through increased acetylation, nuclear translocation and DNA binding activity of the NF-κB subunit RELA/p65." (PMID 32992948, 2020). "The over-expression of genes coding for RelA/NF-κB factors has been observed in many tumors, and the dysregulation of NF-κB is believed to promote cell proliferation, motility, invasion and metastasis in most tumors including prostate cancer." (PMID 26010447, 2015). "Finally, silencing of RELA or STAT3 specifically in TLR9+ tumor-propagating cells inhibits growth of established prostate cancers in vivo." (PMID 26046794, 2015). "Whether RelA–RelB complexes exist in prostate cancer cells remains to be elucidated, but our results justify further investigation." (PMID 16205698, 2005). "The enhancement of VSV oncolysis by vorinostat in prostate cancer cells was traced back to the reversible induction of nuclear factor kappa B (NF-κB) signalling through increased acetylation, nuclear translocation and DNA binding activity of the NF-κB subunit RELA/p65." (PMID 26751469, 2016). "Hence, RelA appears to play a role in the progression of prostate cancer but little is known about the status of other NF-κB family members, and no simultaneous analysis of the subcellular localisation of these subunits has been previously reported in prostate tissues." (PMID 16205698, 2005).
prostate carcinoma (continued). "In prostate cancer cells, KCNJ2 promotes proliferation by binding to the RELA protein in the nucleus, thereby activating the NF-κB signaling pathway." (PMID 38553531, 2024). "The Coremine website finds approximately 18, 250, and 4 articles for FOXP1, RELA, and KDM2B related to prostate cancer." (PMID 37403016, 2023). "A coculture model using prostate cancer PC3 cells and osteoblast hFOB cells to simulate prostate cancer metastasis to bone has been used to evaluate the anti-RelA siRNA delivery by cationic BCD." (PMID 35631507, 2022). "Taken together, our results suggest that NF-κB/RELA and STAT3 cooperate to various extents in orchestrating expression of TLR9-induced prostate cancer stem cell-related genes." (PMID 26046794, 2015). "Bortezomib, a proteasome inhibitor that blocks IĸB degradation and RelA activation, and BS345541, an inhibitor of IKKβ kinase activity have been evaluated in the management of prostate cancer." (PMID 26435478, 2015). "The IPA analysis of our RNAseq data suggested NF-κB/RELA and STAT3 as top mediators of TLR9-dependent gene expression in prostate cancer cells." (PMID 26046794, 2015). "Among these six, HLF, JUN, c-MYC, EGR1, SMAD1, and HIF1A, were also identified as PTEN-controlled TFs, and four, ESR2, MYB, RELA, and USF1, as prostate cancer-related TFs." (PMID 22347425, 2012). "In our study, Ang1–7 decreased the mRNA level of RELA, RELB and REL gene, thus Ang1–7 might potentially contributes to the suppression of prostate cancer." (PMID 30361641, 2018). "Finally, we demonstrated the feasibility of using TLR9-targeted siRNA delivery to block RELA- and STAT3-dependent prostate cancer cell self-renewal in vivo." (PMID 26046794, 2015). "This suggests that both canonical (RelA, p50) and the noncanonical (e.g., RelB, p52) NF-κB subunits can be activated in prostate cancer cells, whereas c-Rel remains inactive." (PMID 16205698, 2005).
COVID-19 (29 papers, 2020 to 2025). A disease caused by infection with severe acute respiratory syndrome coronavirus 2. "Determination of the putative TFs involved in the regulation of the DEGs implicated in COVID-19 and DM showed that SPI1 and RELA are involved in the expression of commonly upregulated genes in COVID-19, T1D and T2D." (PMID 34260684, 2021). "Prediction of the putative transcription factors involved in the upregulation of genes in COVID-19 and DM identified RELA to be implicated in both PBMCs and pancreas." (PMID 34260684, 2021). "The TF RELA has been increasingly recognized as a crucial modulator of the response to SARS-CoV-2 infection and is part of the NF-κB complex, along with RELB31, which is differentially expressed in MERS-CoV and SARS-CoV-2 infected cell lines." (PMID 34031419, 2021). "There were three target genes (JUN, RELA, and AKT1) with a greater degree of significance, and they were identified as potentially relevant genes involved in the processes of HLJDD therapy of COVID-19-associated AKI." (PMID 37533739, 2023). "The underlying mechanisms of kaempferol against COVID-19/PF co-occurrence may be related to bind to EGFR, SRC, MAPK3, MAPK1, MAPK8, AKT1, RELA and PIK3CA." (PMID 35754492, 2022). "Thus, three targets (RELA, TNF, and VEGFA) linked to the MAPK signaling pathway might be promising targets for use against COVID-19." (PMID 35678652, 2022). "RELA may play an important role in the infection of COVID-19." (PMID 33029094, 2020). "Analysis of the transcription factors using the TRRUST database from our data (212 DEGs from GSE36854 and GSE21001) for MPXV infection and COVID-19 database by Metascape identified JUN, REL, STAT3, NFKB1, RELA, SP1, and so on." (PMID 37006463, 2023). "We screened the genes based on their degree values and identified RELA, BCL2, JUN, FOS, and MAPK1 as possible core target genes for puerarin in treatment of COVID-19/COAD." (PMID 35677450, 2022). "In fact, when we compared the expression levels of the genes duplicated in NFKB1, RELA, and H3K36me3 in GSE152418 between the COVID-19 patients and healthy subjects, we observed a decrease in expression levels in the COVID-19 patients." (PMID 34456333, 2021). "In silico analysis of deregulated lncRNA in SARS-CoV-2, infected cells or tissues from COVID-19 patients provided comprehensive information of their target genes/proteins and mechanism of deregulation lncRNAs by IRFs, STATs, MYC, and RelA/p65." (PMID 34940755, 2021). "The main active ingredients of AE against COVID-19 were quercetin, kaempferol and luteolin, and the important targets were IL-6, MAPK1, MAPK8, IL-1β, and RELA." (PMID 33658066, 2021). "According to the results of cytoscape, the targets of JFBDS for treating COVID-19 mainly contained EGFR, PIK3CA, lymphocyte-specific protein tyrosine kinase (LCK), mitogen-activated protein kinase 1 (MAPK1), MAPK3, MAPK8, STAT3, TNF, IL2 and RELA." (PMID 35165507, 2022). "Upregulated genes in early COVID-19 mortality included many involved with interferon signaling (e.g., GBP2, ISG15), the NF-κB pathway (e.g., NFKB2, NFKBIA), and TNF-α and IL-1 signaling (e.g., TANK, NOD1, RELA)." (PMID 35446789, 2022). "By using Cytoscape software to visualize the degree of each gene in the PPI network, we found that RELA, BCL2, JUN, FOS, and MAPK1 had the highest degree, suggesting that the five genes might be core targets of puerarin in COVID-19/COAD comorbidity." (PMID 35677450, 2022). "NF-kB signaling pathway genes (NFKBIA, NFKB1, RELA, NFKB2) were up-regulated in COVID-19 patients." (PMID 36380355, 2022).
COVID-19 (continued). "The results demonstrated that the levels of PAD4, RELA, PKC, SYK and ERK gene expression were signifFicantly increased after healthy neutrophils were incubated with the plasma of COVID-19 patients (p < 0.05)." (PMID 35563204, 2022). "Moreover, the upregulated genes (PAD4, RELA, PKC, SYK, and ERK) after incubation with COVID-19 plasma were significantly decreased by enoxaparin pretreatment." (PMID 35563204, 2022). "We hypothesize that RELA, JUN, NF-κB1, NF-κB2, and FOS are the main targets of puerarin in the therapy of EHF/COVID-19 based on protein interactions." (PMID 35663983, 2022). "In this study, 44 potential targets were obtained through the intersection of the disease targets of COVID-19 and the action targets of AE, which are mainly related to inflammatory or immune factors, such as IL-6, MAPK1, MAPK8, IL1B, RELA, CXCL-8, CCL2, and PTGS2." (PMID 33658066, 2021). "The two main TFs that regulate the shared DEGs between COVID-19 and DM are ‘SPI1’ and ‘RELA’." (PMID 34260684, 2021). "In addition, we provided several potential targets for COVID-19 AKI treatment, mainly IL6, VEGFA and RELA, which may help to develop new therapeutic strategies." (PMID 37274117, 2023). "The RELA was directly enriched in 17 out of 18 signaling pathways by the MAPK signaling pathway, indicating that the MAPK signaling pathway might be a hub signaling pathway in LE against COVID-19." (PMID 35678652, 2022).
pancreatic cancer (25 papers, 2007 to 2026). "Previously, it has been shown that the upregulation of RelA/p65 gene expression is associated with the activation of the NF–κB signaling pathway in pancreatic cancer." (PMID 36012158, 2022). "Moreover, analysis of samples from patients with pancreatic cancer from the TCGA database, confirmed that the expression levels of RELA and miR-21 were positively associated." (PMID 35812178, 2022). "Furthermore, conventional chemotherapeutics like gemcitabine or paclitaxel are often associated with high resistance rates in pancreatic neoplasms, which is partly due to a constitutively activated RelA/NF-κB pathway." (PMID 19912635, 2009). "The finding that HDAC activity is linked to the activity of RelA/p65 in pancreatic carcinoma in vivo could be also confirmed in an in vitro cell culture model, where treatment of cells with the HDI SAHA led to a markedly decrease in nuclear translocation and binding activity of RelA/p65." (PMID 19912635, 2009). "This study provides critical insight into the regulatory dynamics of NF-κB signaling in pancreatic cancer and highlights the specialized functions of RELA and RELB in modulating gene expression and tumor-microenvironment interactions." (PMID 41844578, 2026). "RELA, one of the components of the NF-κB signaling pathway, modulates various cell biological functions in pancreatic cancer 32-34." (PMID 35812178, 2022). "For example, RELA binds to the promoter region of nuclear paraspeckle assembly transcript 1 to regulate its expression, which therefore modulates pancreatic cancer cell proliferation and migration." (PMID 35812178, 2022). "For instance, NEAT1 can sponge miR-302a-3p, which is a tumor-suppressive molecule that suppresses the translation of RELA mRNA, thereby upregulating RELA and increasing the migration and proliferation capacity of pancreatic cancer cells." (PMID 36011001, 2022). "In one study, transiently silenced RelA increased Gemcitabine-induced cell killing, while in another study selective knockdown of RelA in combination with pyruvate dehydrogenase kinase (PDK1/2) enhanced radiation sensitivity of pancreatic cancer cells." (PMID 35402225, 2022). "According to the recent report, lncRNA-NEAT1/miR-302a regulated the expression of RELA (p65), a component of NF-κB family, in pancreatic cancer." (PMID 35651786, 2022). "For example, inactivation of RelA or the TGFβ pathway in mouse models of Kras‐driven pancreatic cancer accelerated pancreatic cancer formation by inhibiting the SASP." (PMID 30614183, 2019). "Our experiments also show that PKM2 translocates to the nucleus during hypoxia and furthermore, interacts with the NF-κB subunit p65/RelA in pancreatic cancer cells, in line with data by Xu and colleagues." (PMID 26739387, 2016). "Due to the pivotal role of RelA/p65 in the tumorigenesis of pancreatic carcinoma we correlated our findings with RelA/p65 expression status." (PMID 19912635, 2009). "Due to the pivotal role of RelA/p65 in the tumorigenesis of pancreatic neoplasia we examined the expression of class I HDACs 1, 2 and 3 in a large cohort of human pancreatic carcinomas and correlated our findings with RelA/p65 expression status." (PMID 19912635, 2009). "In line with activated IKK, the NF-κB subunit RelA/p65 is nuclear translocated in around 45 to 70% of pancreatic cancers." (PMID 18652674, 2008). "Furthermore, through GEPIA2 and HPA databases, we identified that RELA is elevated in pancreatic cancer tissue." (PMID 35812178, 2022). "We also conducted EMSA using nuclear extract from the pancreatic cancer cell line PK8 to determine whether the inhibitory effect of RelA would be observed in the presence of other proteins." (PMID 33266352, 2020). "RelA RNA-interference (RNAi) was shown to synergize with gemcitabine in pancreatic cancer cells." (PMID 31277415, 2019).
pancreatic cancer (continued). "Given the fact that the inducible but not constitutive NF-κB activity prevents death receptor mediated signaling in PDAC cells, the present study aimed to identify RelA target genes jointly responsible for TRAIL mediated apoptosis resistance in pancreatic cancer cells." (PMID 29867042, 2018). "For example, the inhibition of NF-κB by bortezomib (a proteasome inhibitor) sensitized NSCLC to gemcitabine-induced apoptosis, and the silencing of the NF-κB p65/relA subunit with siRNA increased the effectiveness of gemcitabine in a subset of pancreatic cancer cells." (PMID 21843371, 2011). "Furthermore, they profiled a small set of pancreatic tumours immunohistochemically and detected nuclear RelA." (PMID 17622249, 2007). "Thus, compounds with low molecular weight that inhibit RelA may be used as drugs to prevent treatment resistance in pancreatic cancer." (PMID 33266352, 2020). "Furthermore, we could demonstrate that HDAC inhibitors are effective in inhibiting nuclear activation and binding capability of RelA/p65 in pancreatic cancer cells." (PMID 19912635, 2009). "To further establish a link between ATX and NF-κB, we measured the expression of RELA after ATX inhibition in mice with IOA-289, which is now in a Phase 1B trial for treating pancreatic cancer." (PMID 38201482, 2023). "In conclusion, we demonstrated that class I HDACs are overexpressed in pancreatic cancer and that high class I HDAC expression is significantly correlated to nuclear translocation of the transcription factor RelA/p65 in pancreatic adenocarcinoma." (PMID 19912635, 2009). "Results presented here demonstrate our novel observation that pancreatic cancer cells become more sensitive to Ref-1 redox inhibition when PRDX1 expression is decreased and when RelA is present in the cells indicating a novel interplay between PRDX1, Ref-1, and RelA." (PMID 35402225, 2022). "The actual reasons for the overexpression of RelA in pancreatic cancer are not clear." (PMID 17622249, 2007).